ATG9A (autophagy related 9A)
Diseases named in the same sentence as ATG9A in open-access papers (continued):
Sharing a sentence is not in itself a finding about the gene and the disease.
gastric cancer (1 paper, 2018). A primary or metastatic malignant neoplasm involving the stomach. "In contrast, it has been recently suggested that the long non-coding RNA (lncRNA) HAGLROS was induced in gastric cancers and that its down-regulation led to decreased migration and invasion of gastric cancer cells, but also to increased ATG9A/B levels, suggesting an anti-tumor role of ATG9A." (PMID 30563263, 2018).
gastric tumor (1 paper, 2023). "Among autophagy genes in the Reactome database, PRMT1 was negatively correlated with genes such as ATG9A, DYNC1H1, EPAS1, PINK1, TSC1, TUBB6, and ULK1 in gastric tumor tissues (STAD-TCGA) and positively correlated with HMMR, ESCO2, CHAC2, and NUDT6 (STAD-TCGA)." (PMID 37564212, 2023).
inflammatory skin disease (1 paper, 2026). Inflammatory skin disorders covers a broad category that includes many conditions ranging in severity, from mild itching to grave medical health complications These disorders are common in people of all ages and races. "In a recent study published in Immunity, we discovered that ATG9A-dependent, LC3-independent autophagy facilitates the degradation of multiple inflammatory signaling complexes to prevent an inflammatory skin disease." (PMID 41542114, 2026). "Mice lacking ATG9A in the skin spontaneously developed a severe inflammatory skin disorder, characterized by back skin lesions, epidermal hyperplasia, compromised skin barrier integrity and systemic inflammation." (PMID 41542114, 2026).
invasive ductal carcinomas (1 paper, 2018). "Furthermore, a recent study reported a decrease in ATG9A mRNA expression in breast invasive ductal carcinomas, compared to adjacent healthy tissues, and this decrease was linked with increased promoter methylation." (PMID 30563263, 2018).
lymphoma (1 paper, 2025). A malignant (clonal) proliferation of B- lymphocytes or T- lymphocytes which involves the lymph nodes, bone marrow and/or extranodal sites. "Moreover, Beclin 2 interacts with STX5 to promote the fusion of ATG9A-mediated vesicles with autophagosomes, degrading MEKK3 and thus suppressing the development of lymphoma." (PMID 39735677, 2025).
mesothelioma (1 paper, 2022). A usually malignant and aggressive neoplasm of the mesothelium which is often associated with exposure to asbestos. "The risk score for the mesothelioma TCGA cohort was calculated as follows: risk score = (0.782 × PGAM5 expression) + (1.545 × ATG9A expression)." (PMID 36292980, 2022).
myocardial infarction (1 paper, 2023). Gross necrosis of the myocardium, as a result of interruption of the blood supply to the area, as in coronary thrombosis. "miR-15b-5p targets SMAD Family Member 7 (SMAD7), Notch Receptor 2 (NOTCH2), an important player in the regeneration and cardiac repair post myocardial infarction, and Autophagy Related 9A (ATG9A)." (PMID 38132140, 2023).
Obesity (1 paper, 2016). Accumulation of substantial excess body fat. "Interestingly, obesity induced by a high fat-diet or Bif-1 deficiency downregulates the expression of proteins involved in the autophagy-lysosomal pathway, including Atg9a and Lamp1 in the adipose tissue." (PMID 26857140, 2016).
osteosarcoma (1 paper, 2021). A usually aggressive malignant bone-forming mesenchymal neoplasm, predominantly affecting adolescents and young adults. "KD of ATG9A in the human osteosarcoma U-2 OS cell line similarly increased LD number and size, indicating that these effects were not limited to HeLa cells." (PMID 34799570, 2021).
ovarian failure (1 paper, 2022). "Although the precise role of ATG9A in male fertility is yet to be elucidated, a study reported that the loss of ATG9A function triggers ovarian failure (primary ovarian insufficiency) in COS-7 cells." (PMID 35173218, 2022).
pancreatic ductal adenocarcinoma (1 paper, 2018). An infiltrating adenocarcinoma that arises from the epithelial cells of the pancreas. "Another study showed that miR-29a, which targets the ATG9A and TFEB mRNAs, is down-regulated in Pancreatic Ductal Adenocarcinoma (PDAC) leading to increased ATG9A levels, autophagy flux and resistance to gemcitabine, as well as increased cancer cell migration." (PMID 30563263, 2018).
parasitic infection (1 paper, 2020). "Genetic variants of interest identified in several immune related genes for all the antibody response and parasitic infection traits: IBDV (TOLLIP, ANGPTL5, BCL9, THEMIS2), MDV (GRM7), SG (MAP3K21), Eimeria (TOM1L1), and cestodes (TNFAIP1, ATG9A, NOS2)." (PMID 33193617, 2020).
progeria (1 paper, 2023). "The progeria phenotype of AT-1 sTg mice is mechanistically linked to the increased acetylation of ER-bound ATG9A, resulting in defective proteostatic control." (PMID 37689798, 2023).
prostatic hyperplasia (1 paper, 2018). "The current study confirmed that ATG9A knockdown by shRNA inhibited autophagy in prostate stromal fibroblasts, indicating that ATG9A also plays vital roles in regulating autophagy in prostatic hyperplasia." (PMID 29568063, 2018).
rosacea (1 paper, 2023). A chronic erythematous skin disorder that affects the face. "The expression of autophagy-related genes (ATG9A, ATG10, ATG12, and PIK3C3) was evidently decreased in rosacea lesions compared with normal skin tissues in the GSE65914 dataset." (PMID 36937834, 2023).
triple-negative breast carcinoma (1 paper, 2018). An invasive breast carcinoma which is negative for expression of estrogen receptor (ER), progesterone receptor (PR), and human epidermal growth factor receptor 2 (HER2). "To corroborate these in vivo data, we designed shRNA- and CRISPR/Cas9-driven inhibition of ATG9A expression in the triple negative breast cancer cell line MDA-MB-436, in order to determine its role in the regulation of cancer phenotypes." (PMID 30563263, 2018). "Our data showed, for the first time, that one autophagy gene, ATG9A, presented a significant increase in triple negative breast cancer patients compared to healthy adjacent tissues and correlated with the expression of the proliferative marker KI67." (PMID 30563263, 2018). "Taken together, our results highlight, for the first time, the clinical relevance of ATG9A as a therapeutic target in triple negative breast cancer patients." (PMID 30563263, 2018).
uveal melanoma (1 paper, 2022). A melanoma derived from melanocytes of the uveal tract. "The risk score for the uveal melanoma TCGA cohort was calculated as follows: risk score = (0.8578 × SQSTM1 expression) + (−1.2004 × ATG9A expression) + (−2.0815 × GABARAPL1 expression)." (PMID 36292980, 2022).
varicocele (1 paper, 2025). A condition characterized by the dilated tortuous veins of the spermatic cord with a marked left-sided predominance. "Finally, our post varicocele sclero-embolization proteomic data revealed a downregulation of autophagy-related proteins, including ATG9A, a crucial protein for autophagosomal membrane expansion." (PMID 40700278, 2025).
vitiligo (1 paper, 2024). Generalized well circumscribed patches of leukoderma that are generally distributed over symmetric body locations and is due to autoimmune destruction of melanocytes.
tumor (18 papers, 2017 to 2025). "Specifically, lipidomic data indicate that macrophage co-culture triggers ROS-mediated lipid peroxidation in ATG9A-deficient tumor cells, increasing membrane vulnerability." (PMID 40595560, 2025). "The mechanism underlying these tumor-suppressive activities of miR-29-3p involves the downregulation of autophagy-related 9A (ATG9A) and transcription factor EB (TFEB), which control the trafficking of autophagosome and lysosomal function." (PMID 33435156, 2021). "Given that ATG9A deficiency in tumor leads to increased inflammatory cytokine secretion, we aimed to characterize the tumor associated and cytotoxic macrophages in control and ATG9A KO tumors in vivo, which may have mechanistic and therapeutic relevance." (PMID 40595560, 2025). "We then investigated whether a decrease in ATG9A expression in the MDA-MB-436 cell line would alter its tumor-linked features such as in vitro proliferation and invasion." (PMID 30563263, 2018). "In order to determine whether the high ATG9A mRNA levels quantified in TN tumors were a cause or a consequence of tumor development, we decided to inhibit ATG9A expression in the TNBC cell line MDA-MB-436." (PMID 30563263, 2018). "These insights provide a strong rationale for further investigation of ATG9A-targeted approaches as a means to augment macrophage-based therapies, and to study its role in other tumor types, in the comprehensive fight against cancer." (PMID 40595560, 2025). "This indicates ATG9A mediates lipid droplet delivery to lysosomes and lysosome delivery to the plasma membrane in response to tumor-targeting macrophage damage." (PMID 40595560, 2025). "This highlights that depleting regulatory macrophages via CSF1R inhibition enhances cytotoxic macrophage activity, leading to robust tumor eradication when ATG9A-dependent membrane repair is impaired." (PMID 40595560, 2025). "Depleting non-cytotoxic macrophages using CSF1R inhibition while preventing ATG9A-mediated tumor membrane repair enhances the anti-tumor activity of therapeutic antibodies in mice." (PMID 40595560, 2025). "The goal of this study was to determine the role of miR-195-5p and the autophagy-related protein ATG9A in tumour metastasis, epithelial – mesenchymal transition (EMT), apoptosis, and autophagy of CC cells." (PMID 37782756, 2023). "Another potential regulator of the retrieval step is the tumor suppressor, miR-34a, which has recently been identified as an inhibitor of the autophagic flux and a direct regulator of ATG9A and ATG4B in mammalian cells." (PMID 36000264, 2022). "In orthotopic patient-derived GBM xenograft models, inhibiting ATG9A expression can effectively stop tumor development." (PMID 34204169, 2021). "When we compared the ATG9A score with the percentage of tumor cells expressing the proliferative marker KI67, we observed a strong correlation between ATG9 and KI67 (p < 0.001, and Pearson r 0.79)." (PMID 30563263, 2018). "As expected, the ATG9A staining was significantly higher in 15 out of 21 patients (71%; p < 0.0001), four were unchanged, and only two were decreased in the tumor cells compared to the normal adjacent tissue (mean expression of 2.87 and 5.3 in normal and tumoral tissues, respectively)." (PMID 30563263, 2018). "To date, only seven out of the 80 patients from our cohort presented a cancer recurrence, and amongst them, five presented an increase in ATG9A mRNA levels in tumor cells compared to the healthy adjacent tissues (3/5 patients were diagnosed with TN, and 2/5 with Luminal B)." (PMID 30563263, 2018). "Of the 21 MRGs, ATG9A, PGAM5, SQSTM1, and GABARAPL1 were differentially expressed at the transcriptomic level between tumor and normal tissues." (PMID 36292980, 2022). "Trehalose significantly increased cell death (P < 0.001 vs. UVB group), exhibiting a clearance effect on tumor cells, and TIMP3 and ATG9A siRNA inhibited trehalose-induced cell death under UVB exposure conditions (P < 0.01 vs. UVB + TRE group)." (PMID 35450405, 2022).
tumor (continued). "Compared with normal tissues, tumor tissues showed significantly higher mRNA levels of the following key autophagy genes: ATG5, ATG7, ATG3, ATG9A, ATG9B, ATG12, AMBRA1, and NBR1." (PMID 32582551, 2020). "To do so, we analyzed the expression of the ATG9A protein in eight TNBC biopsies and compared its expression in the tumor compared to the healthy adjacent tissue." (PMID 30563263, 2018). "In this study, firstly, TMEM74 was shown to increase autophagic flux in diverse tumor cell lines and interact with ATG16L1 and ATG9A to induce autophagy." (PMID 29048433, 2017). "ATG9A, a member of the autophagy pathway, was one major hit without a clear connection to tumor phagocytosis or cytotoxicity." (PMID 40595560, 2025). "While we determined that macrophages induce tumor membrane peroxidation that cannot be efficiently repaired in the absence of ATG9A, we next sought to determine the precise nature of the macrophages responsible for this type of damage, in vivo." (PMID 40595560, 2025). "From the results, we noticed that tumor cells highly expressed AUP1 significantly correlated with proliferation marker (MCM2, MCM6), PI3K-AKT-MTOR pathway (Akt1, TSC1, mTOR, Foxo1), and autophagy signaling (Atg3, Atg4B, Atg4D, Atg7, Atg9A, Atg16L1) in IDH wildtype tumor cells." (PMID 37029364, 2023). "Several ATG proteins, as well as their corresponding core complexes, such as LC3 ubiquitin-like binding system, ATG9A transport system, ATG12, autophagy-specific class III PI3K complex, and ULK 1/2 kinase core complex, are the key regulatory factors of tumor occurrence and progression." (PMID 35677537, 2022). "Silencing ATG9A will result in reduced GBM proliferation and delayed tumor progression in vitro." (PMID 34204169, 2021). "To understand the mechanism of this differential effect, we found that ferroptosis inducers upregulate mRNAs encoding multiple direct and indirect autophagy stimulators, such as ATG16L2, ATG9A, ATG4D, GABARAP, SQSTM/p62, SEC23A and BAX, in tumor cells growing in 2D but not in 3D culture." (PMID 37658069, 2023).
cancer (16 papers, 2015 to 2025). A tumor composed of atypical neoplastic, often pleomorphic cells that invade other tissues. "Our study demonstrates that ATG9A deficiency sensitizes cancer cells to macrophage-mediated killing, particularly in the presence of antitumor antibodies or CAR, which provide target specificity for cytotoxic macrophages." (PMID 40595560, 2025). "We also found lower ATG9A mRNA is associated with better survival in several additional cancer types." (PMID 40595560, 2025). "Proteomic and lipidomic analyses reveal that ATG9A deficiency impairs the cancer cell response to macrophage-induced plasma membrane damage through defective lysosomal exocytosis, reduced ceramide production, and disrupted caveolar endocytosis." (PMID 40595560, 2025). "Disruption of these processes in ATG9A-deficient cells reveals potential vulnerabilities in membrane repair pathways that may be exploited for cancer therapy." (PMID 40595560, 2025). "To determine whether the genetic invalidation of ATG9A expression also led to an inhibition of cancer-associated phenotypes, similar to the ones already observed in the sh-ATG9A clones, we quantified the proliferation rate of these cells using a MTT assay." (PMID 30563263, 2018). "In vitro and in vivo, ATG9A depletion in cancer cells sensitizes them to macrophage-mediated killing." (PMID 40595560, 2025). "Given its promising phenotype scores, strong link to poor cancer prognosis, as well as relatively unexplored relevance to macrophage response, we focused on ATG9A in our following study." (PMID 40595560, 2025). "We next examined exactly how cancer cells utilize ATG9A to facilitate repair of the plasma membrane." (PMID 40595560, 2025). "To validate this effect with a different CAR construct, we generated HER2-CAR macrophages, which similarly showed enhanced cancer cell sensitization after ATG9A KO." (PMID 40595560, 2025). "Our study highlights the crucial role of ATG9A in sensitizing cancer cells to macrophage-induced membrane damage and killing, which is independent of autophagy." (PMID 40595560, 2025). "By employing CRISPR screening in CAR-macrophage and cancer cell co-culture system, the authors identify depletion of ATG9A on cancer cells sensitizes them to macrophage-mediated killing, which can be synergic with CSF1R inhibition in cancer treatment." (PMID 40595560, 2025). "Although its role in macrophage sensitization was unclear, it has been shown that ATG9A regulates cancer cell response to T-cell-mediated killing through the IFN-γ pathway." (PMID 40595560, 2025). "This highlights a unique, autophagy independent role for ATG9A in regulating cancer cell response to, and repair of macrophage-induced plasma membrane damage." (PMID 40595560, 2025). "Their finding demonstrated that Atg9A inhibition suppressed in vitro cancer characteristics, indicating the potential of Atg9A as a novel therapeutic target for TNBC." (PMID 40723786, 2025). "Loss of ATG9A and ATG9B genes or disruption of the autophagy pathway is associated with a vast variety of cancers." (PMID 40949798, 2025). "In conclusion, dual CRISPR screens identified ATG9A and UBAP1 as crucial regulators of cancer cell susceptibility to CAR-macrophage-induced cytotoxicity." (PMID 40595560, 2025). "Significantly more PI-positive cells were observed in ATG9A KO compared to control shortly after co-culture, indicating increased cancer cell plasma membrane damage induced by macrophages in the absence of ATG9A." (PMID 40595560, 2025). "Our study demonstrates that ATG9A knockout sensitizes cancer cells to macrophage-mediated killing through mechanisms requiring direct cell-cell contact, involving direct membrane damage rather than whole cell phagocytosis." (PMID 40595560, 2025). "After co-culture with CAR-Ms, only ATG9A KO showed increased membrane damage, and similarly only ATG9A KO resulted in increased cancer cell killing." (PMID 40595560, 2025).